CD33 (CD33 molecule)
Diseases named in the same sentence as CD33 in open-access papers (continued):
Sharing a sentence is not in itself a finding about the gene and the disease.
tumor (continued). "Contrary to other monoclonal antibody-based strategies, escape mechanisms towards gemtuzumab ozogamicin are not driven by downregulation of CD33 on tumor cells, but rather by chemoresistance due to the extracellular efflux of calicheamicin by ATP-dependant multidrug resistance (MDR) pumps." (PMID 22272203, 2012). "In addition, we observed that the repeated administrations of anti-CD33.CAR-transduced EBV-CTLs did not result in the selection of CD33-negative tumor clones, that would be resistant to our therapeutic approach." (PMID 22272203, 2012). "Notably, ECM3+/IFN− tumors showed low tumor‐infiltrating lymphocytes, high levels of CD33‐positive cells, absence of PD‐1 expression, or low expression of PD‐L1, as suggested by immune profiles and immune‐histochemical analysis on an independent cohort of 131 HGBCs." (PMID 33523584, 2021). "For instance, we recently demonstrated the increase in vivo persistence and efficacy of anti-CD33 CAR-T metabolically enhanced by inserting ASS1 and OTC expression domains such that these cells could re-synthesized arginine from citrulline discarded by the tumor cells." (PMID 34094976, 2021). "The ex vivo biodistribution study confirmed the significant higher tumor targeting for anti-CD33 Nbs (tumor uptake from 1.91 ± 0.64%IA/g to 2.53 ± 0.69%IA/g), compared to Nb_16 (tumor uptake of 0.70 ± 0.13%IA/g) and to the non-targeting control 99mTc-ctrl_Nb (tumor uptake of 0.16 ± 0.04%IA/g)." (PMID 31906437, 2020). "However, a number of anti-tumor antibodies target molecules expressed by tumor cells belonging to the hematopoietic lineage and, hence, also target their normal cell counterparts, notably lymphocytes (anti-CD20, -CD52, -CD38, SLAMF7, etc.)and myeloid cells (anti-CD30, -CD33, etc.)." (PMID 28855903, 2017). "Importantly, these normal skin samples had no detectable hyperplasia or neoplasia that could explain the increased presence of CD33+ MDSCs." (PMID 27272654, 2016). "Additionally, considering the transient but significant tumor response, the authors suggested that CAR.CD33 T-cells could be used as a ‘bridge’ to an allo-HSCT, thus rescuing possible off-target myelotoxic effects of the CAR.CD33 T-cells with the HSCT." (PMID 27907031, 2016). "Conversely, patients without lymphatic tumor emboli showed increased proportions of postoperative CD11b+CD14− and CD33+CD14− cells." (PMID 39749673, 2025). "The tumor cells were negative for CD25, myeloperoxidase (MPO), CD34, CD123, CD138, and CD163 but strongly positive for CD117, CD13, and CD33 and focally positive for mast cell tryptase, CD30, CD43, and CD68." (PMID 39404971, 2024). "A high percentage of infiltrating CD33 CAR-NK cells into the bone marrow and spleen of treated mice and a strong reduction of tumor burden at day 21 of treatment was observed, with no signs of CRS or GvHD." (PMID 38694825, 2024). "Immunohistochemically, the tumor cells were negative for CD20, CD79a, CD3, CD5, c-kit, CD34, and TdT and positive for myeloperoxidase, CD33, CD68, and CD163." (PMID 34970464, 2021). "There was a negative correlation between stromal CD33+ cells and CD14 expression in the tumor stroma (r = -0.303, p = 0.0073)." (PMID 33625532, 2021). "We found that in contrast to peripheral blood, in which the level of CD33+CD11b+HLA-DR− MDSCs did not increase in this relatively early stage of LARC, their levels within the tumor were significantly higher relative to the adjacent normal rectal mucosa." (PMID 32903466, 2020). "We found that HMGB1, secreted from tumor cells treated with DOC-based chemotherapy, did not influence the presence of suppressive myeloid (CD33+/CD11b+ MDSC) or Foxp3+Treg cells in tumors." (PMID 30744691, 2019). "In most patients, CD33+CD14− cells were the predominant macrophage population in NTB, but not in the tumor." (PMID 27195119, 2016).
tumor (continued). "Of note, despite the lack of cytokine addition or EBV stimulation, anti-CD33.CAR-transduced EBV-CTLs were able to home and infiltrate the tumor, where they exerted a significant anti-tumor activity." (PMID 22272203, 2012). "However, when engineered with CAR, CAR33-T cells demonstrated efficient killing of all CD33+ AML tumor cells while showing no cytotoxicity towards CD33- tumor cells, demonstrating their reliance on the CAR33-CD33 interaction." (PMID 39893165, 2025). "Unlike CD33, CD123, and CLEC12A, FLT3 off-tumor expression is largely confined to a subset of HSPCs and is much lower than on malignant cells, which may provide a window for targeting AML without profound myeloablation." (PMID 39095991, 2024). "Combining CC-96191FC-SILENT with the parent CD33 mAb I07 did not restore the full cytolytic activity of CC-96191, suggesting that the co-engagement of NKG2D and CD16a on NK cells by the same molecule is important for anti-tumor activity." (PMID 38473239, 2024). "Similarly, in NK cells, efforts have been directed towards developing bispecific or trispecific NK cell engagers (TriKE) targeting NKG2D, NKp46, NKp30 with or without CD16 targeting, and tumor antigens like CD30 and CD33." (PMID 38785789, 2024). "We next evaluated C-JUN impact on CAR T cells with different costimulation domains and observed that mice in the CD33 bbz-C-JUN and CD33 28z-C-JUN CAR T cell treatment groups had comparable effects in enhancing tumor control compared with non-C-JUN CAR T cells." (PMID 39039086, 2024). "Tumor immunophenotype was characterized by a strong expression of conventional myeloid antigens (CD13, CD33, CD15, MPO), although no monocytic (CD14, CD64, CD11c, CD11b, lysozyme), megakaryoblastic (CD61, CD41) and lymphoid (CD7, CD19, iCD79a, CD56, CD2) markers were found." (PMID 36980947, 2023). "Indeed, we found that, following cocultures with MV4-11 tumor cells, SAR T cell activity was reversible over time in the absence of taFv redosing, unlike human anti-CD33 CAR T cells." (PMID 33414484, 2021). "Because CD33 molecule is expressed on healthy and neoplastic myeloid cells, it is not an optimal target for CAR therapy and may result in off-tumor toxicity and destruction of healthy myeloid cells." (PMID 34203935, 2021). "Also, CD33+, STAT3+, and pSTAT3+ cells in BC tissue are significantly higher in the tumor tissues compared to the tumor margin and absent or low in healthy controls." (PMID 33679700, 2020). "Similarly, in GBM tumor masses, the predominant presence of neutrophilic (CD33+CD15+CD14−HLA-DR−) and negative lineage (CD33+CD15−CD14−HLA-DR−) MDSCs has been shown." (PMID 32182988, 2020). "Notably, tumor cell eradication in trastuzumab/IL-15-treated HTM is not only achieved by NK-cell activation but also by a stimulation and increased infiltration of CD33+ myeloid cells (e.g., macrophages)." (PMID 27835865, 2017). "Taken together, the binding properties of licMABs enable these molecules to discriminate between CD33 negative and CD47 positive healthy cells, and CD33 and CD47 double positive tumor cells, and to selectively bind to the latter, avoiding undesired side effects." (PMID 28061465, 2017). "Indeed, in vitro tumor cell killing assays demonstrated that Allo15CAR33-NKT cells were markedly more effective at eliminating primary blast cells compared to CAR33-T cells, notably targeting CD33-negative LSPCs, which CAR33-T cells failed to engage." (PMID 39893165, 2025). "Where CD33dim indicates a lower level of CD33 expression and CD11b- indicates no expression of CD11b.Mo-MDSC stands for monocyte-derived myeloid-derived suppressor cells, which play an important role in the regulation of immune responses, inflammation, and the tumor microenvironment." (PMID 39086903, 2024).
tumor (continued). "Similar to other antigens (CD33, Her2, EGFR) which are used as therapeutic targets and that are not tumor cell-specific, first in men studies with novel drugs targeting such new target structures have to be carefully performed, and it has to be determined whether a safe therapeutic window exists." (PMID 22879978, 2012).
cancer (124 papers, 2007 to 2026). A tumor composed of atypical neoplastic, often pleomorphic cells that invade other tissues. "Next, to understand the underlying role of MDSCs in drug resistance and cancer recurrence, CD33+ MDSCs were generated from human PBMC in-vitro." (PMID 38304256, 2023). "This is an important finding, since there was a higher percentage of MDSC in old individuals with predominance of the granulocytic phenotype (CD33+CD11b+CD15+) that has been associated with some types of cancer in humans." (PMID 29910802, 2018). "We find that CD15+CD66+ neutrophils from the PBMCs of both healthy, steady-state subjects, and cancer patients, differentially express CD33, Siglec-5/-14, -7, and -9 based on the expression of CD16." (PMID 40626011, 2025). "Kinetic assessments of DARIC33-induced cancer cell cytotoxicity showed rapid and complete rapamycin-dependent cancer cell killing only when the target antigen CD33 was expressed in cancer cells." (PMID 38502193, 2024). "The polymorphonuclear myeloid-derived suppressor cells (PMN-MDSCs; CD16− CD14− CD11b+ CD33+) play an important role in immune inhibition in the cancer microenvironment, while their role in circulation is still unclear." (PMID 39195280, 2024). "This requirement limits its application to only those patients whose cancer cells meet this criterion, excluding those with low levels of CD33 expression." (PMID 38255313, 2024). "MDSC-like cells generated with A549 and A549-sia cancer cell lines showed a distinct composition of CD33+ cell populations." (PMID 38448555, 2024). "Recent studies have shown that CD33+CD11b+HLA-DR–/lo cells from cancer patients have a complete overlap with monocytic-MDSCs and PMN-MDSCs, which were often defined as cells co-expressing CD14 and CD1537,38." (PMID 36878933, 2023). "Immunofluorescence investigations confirmed that GPR84 was highly expressed in the CD33+ MDSCs of cancer tissues." (PMID 37105980, 2023). "Among them, an anti-CD33 antibody (Gemtuzumab) targeting MDSCs is shown to restore T cell immunity and improve cancer immunotherapy by depleting CD33-expressing MDSCs." (PMID 37843274, 2023). "In one set up, CD33+ MDSCs and cancer cells were cultured in same well to commence receptor-ligand interaction (CD)." (PMID 38304256, 2023). "Flow cytometry of lintuzumab-DFO binding to CD33 expressing human cancer cell lines MV411, HL60, and U937 revealed that the conjugate preserved at least 85% of cold lintuzumab immunoreactivity." (PMID 36235126, 2022). "Increased bone marrow 18F-FDG-uptake accompanies the immunosuppressive cancer microenvironment, represented by increased CD33+ cells and decreased CD8+ T cells." (PMID 36354870, 2022). "The immunosuppressive activity of CRC in our study is also supported by the significantly higher expression of PD-L1 and CD33 in cancer than in normal control." (PMID 33625532, 2021). "For CD33 is overexpressed in MDSCs of cancer patients, combination therapy with gemtuzumab ozogamicin, a CD33 antibody conjugated with a cytotoxic drug from the class of calicheamicins, increased the antitumor activity of CAR T cells by depleting MDSCs." (PMID 34209505, 2021). "MDSCs are a group of heterogenous immature myeloid cells mostly consisting of CD33+/CD11b+/HLA-DR- cells that form an immunosuppressive niche in cancers." (PMID 33718188, 2021). "MDSCs, a population of cells with suppressive activity and measured as CD11b + CD33 + HLA–DR− cells, contribute to the negative regulation of immune responses that occur in cancer." (PMID 34578883, 2021). "There appears to be a mechanism linking HMGB1 to immunosuppression and myeloid cells including TAMs and CD33-positive myeloid cells in patients with malignant tumors, which needs further studies to uncover." (PMID 34257571, 2021). "Here, we show an unexpected human‐specific connection between advanced carcinomas and a member of the CD33‐related family of Siglecs (Sialic acid‐binding Ig‐like lectins) receptors." (PMID 33615152, 2021).
cancer (continued). "The lower number of intralesional CD33+ cells in malignant tumors points to a potential reduction in myeloid cell infiltration." (PMID 33139767, 2020). "Compared to healthy donors, the purified HLA-DR- CD33+ cells from the cancer patients significantly reduced autologous and analogous CD3+ T cell proliferation." (PMID 33679700, 2020). "Hereby, anti-CD33 Nbs can be developed as targeting vehicles to specifically deliver toxins to the target cancer cells, in the so-called antibody–drug conjugates (ADCs)." (PMID 31906437, 2020). "Here we have identified how CD33 marks the MDSCs which are found in the blood and tissues of patients across cancers." (PMID 31462392, 2019). "Incubation of CD33+ MDSCs from cancer patients with ALEXA647 labelled-GO confirmed binding predominantly to the M-MDSC population, and rapid immunotoxin internalisation." (PMID 31462392, 2019). "The study identifies that M-MDSCs and G-MDSCs are transcriptomically different but CD33 is a therapeutic target on peripheral and infiltrating MDSCs across cancer subtypes." (PMID 31462392, 2019). "We performed a thorough literature review concerning all the possible positive prognostic factors not included in our study, finding as possibly critical the role played by cancer stem cells (CSCs, CD33+)." (PMID 31801254, 2019). "The expression of either CD19 or CD33 on the cancer cell surface was sufficient to induce cytolysis via 33-3-19 plus T cells." (PMID 26981773, 2016). "Most importantly, Cox multivariate analysis demonstrated that the density of CD33+/p-STAT1+ cells within the cancer tissue was an independent prognostic factor." (PMID 23307253, 2013). "Of note, withinthe pMDC population, cells with high CD33 expression levels (population B inFigure 2(a)) were significantly decreased in the cancer patients beforetreatment, as compared to the healthy donors (P = .02)." (PMID 18320010, 2007). "CD3/CD33 BsAb, in which one arm targets the CD3 molecule on the surface of T cells and the other arm targets the CD33 antigen on the surface of cancer cells, in this way, the BsAb close the distance between T cells and cancer cells, directing T cells to kill cancer cells directly." (PMID 40211406, 2025). "We found that in addition to CD33 (Siglec-3), Siglec-5/-14, -7, and -9, are differentially expressed on the CD16low and CD16high low-density subsets in both healthy, steady-state subjects, and cancer patients." (PMID 40626011, 2025). "Furthermore, the specific expression of CD33 on cancer cells is crucial for the success of GO, as its effectiveness has been shown to depend on high CD33 expression." (PMID 38255313, 2024). "Our findings collectively suggest that PET imaging using 89Zr-lintuzumab could be a powerful drug development tool to evaluate binding properties of anti-CD33 monoclonal antibodies in preclinical cancer models." (PMID 36235126, 2022). "Our findings collectively suggest that PET imaging using 89Zr-lintuzumab could be a powerful pre-clinical drug development tool to evaluate binding properties of anti-CD33 monoclonal antibodies in preclinical cancer models." (PMID 36235126, 2022). "Interestingly, the percentage of circulating MDSCs (defined by cell surface phenotype, i.e., CD33+CD11b+HLA-DRlow/−) in septic patients was consistent with the range demonstrated to be present in the circulation of cancer patients." (PMID 31722736, 2019). "CD33+ cells from peripheral blood could be differentiated into MDSCs by co-culture with cancer cells including CRC cell lines HCT116 and SW480 in vitro." (PMID 31620141, 2019). "We hypothesised that human MDSC CD33 could similarly be targeted, as a strategy across cancer subtypes." (PMID 31462392, 2019). "The majority of cancer or HLH samples had high intensity of CD33 positivity." (PMID 31462392, 2019).
cancer (continued). "D) The cytotoxicity of unconjugated gemtuzumab antibody (2 μg/ml) against CD33+ patient-derived MDSCs from different cancer subtypes, compared to gemtuzumab ozogamicin (2 μg/ml) and untreated controls, as assessed by flow cytometry with propidium iodide staining." (PMID 31462392, 2019). "We compared the levels of CD33+CD11b+HLA-DR+ myeloid cells between cancer patients and HD." (PMID 28283696, 2017). "We observed a common pattern of up regulation of the polycomb group PRC2 and enrichment for the histone mark H3K27me3 in many cancer cell lines, as well as alterations in Toll-like receptor and interlukin signaling in K562 cells when compared with normal myeloid CD33+ cells." (PMID 23586463, 2013). "MDSCs, which can be characterized by CD11b+ CD33+ expression and divided into several subtypes based on phenotypic, morphologic, and functional heterogeneity, have emerged as major regulators of the immune response in cancer and are the subject of intensive research." (PMID 39927513, 2025). "In addition, mass spectrometry (MS)-based analysis of released N-glycans from cancer patient-derived CD33+ cells revealed a clear increase in the abundance of terminally sialylated N-glycans containing multiple sialic acids compared to that in myeloid cells from healthy donors." (PMID 38448555, 2024). "Although CD33 may also be expressed on normal monocytes and macrophages in healthy individuals, critically it is the MDSCs which represent the bulk of myeloid-cells in the cancer patients who would receive Gemtuzumab ozogamicin." (PMID 31462392, 2019). "For example, the proportion of CD3+CD8+ cytotoxic T cells was higher in T1 than in T2 cancer, and the percentage of CD11b+CD14−/CD33+CD14− PMN-MDSCs was lower in T1 than in T2 cancer." (PMID 41051525, 2025). "Other targets, including TNF receptor superfamily member 17 (TNFRSF17), CD22, CD38, CD33, and C-type lectin domain containing 14A (CLEC14A), demonstrated consistent but lower targeting potential across cancers." (PMID 39439803, 2024). "The interaction network of 50 SHP-1-binding proteins showed that many of them were involved in immune function and cancer signal transduction, such as IL4R, JAK1, CD33." (PMID 39367146, 2024). "Analysis of the CRC dataset from the cancer genome atlas (TCGA) demonstrated a positive correlation between THBS1 and mesenchyme-related genes (VIM and FN1) and pan-myeloid markers (CD14 and CD33)." (PMID 37749092, 2023). "In patients with RCC as well as with other cancers, granulocytic (G) MDSCs (CD33+, HLADR−, CD15+, CD14− dominate over monocytic (M) MDSCs (CD33+, HLADR−, CD15−, CD14+), as seen in mouse models." (PMID 36614308, 2023). "After GO binding to CD33-expressing cancer cells, the ADC–CD33 complex is internalized, followed by intracellular release of N-acetyl gamma calicheamicin dimethyl hydrazide." (PMID 38187390, 2023). "In particular, for the therapy of AML, which requires greater cancer cell specificity, in pioneer studies, CAR T cells targeting antigens CD33, CD44, and CD123 have been developed." (PMID 35990606, 2022). "In human cancer patients, MDSCs are identified as HLA-DR-CD11b+CD14-CD33+ cells that co-express the myeloid differentiation markers, CD11b and CD33, while lacking mature lymphoid and myeloid cell markers, such as HLA-DR, an MHC class II molecule." (PMID 35711434, 2022). "Myeloid-derived suppressor cells (MDSCs; CD34+CD33+CD13+CD15(−)) are a population of myeloid progenitor cells that have been observed to be key players in chronic inflammation and cancer development." (PMID 36358879, 2022). "Researchers have also used CRISPR/Cas9 technology to remove CD33 from hematopoietic stem cells in AML patients, leaving CD33+ cancer cells as the only target of CD33 CAR–T cells." (PMID 36193328, 2022). "These ADCs act by increasing the internalization of cytotoxic small molecules into cells expressing cancer cell membrane proteins, such as CD30 and CD33." (PMID 36346674, 2022).